IL25 (interleukin 25)
Diseases named in the same sentence as IL25 in open-access papers (continued):
Sharing a sentence is not in itself a finding about the gene and the disease.
infection (continued). "The infection induced by a protozoan parasite can reduce IL-25 expression while the administration of rIL-25 protein can help control amebiasis in mice." (PMID 36119076, 2022). "The first circulatory ILC2 wave, which appears on day 5 after infection, was accounted for by IL-25 dependent SI ILC2s." (PMID 35572538, 2022). "In this paper, we analyse the potential role of intestinal microbiota in the production of IL-25, and the subsequent resistance to infection." (PMID 36176223, 2022). "In the small intestine, tuft cells are present in small numbers during homeostasis, but their prevalence increases rapidly upon infection with various Th2-associated pathogens in a manner dependent upon ILC2-derived IL-13 and tuft cell-derived IL-25." (PMID 36073526, 2022). "NB and TM infection models have in common that intestinal tuft-cell derived IL-25 promotes IL-13 release by ILC2s, which in turn elicits further expansion of IL-25 producing tuft cells." (PMID 36430676, 2022). "The notion of ILC2 functional plasticity was first demonstrated through intraperitoneal administration of IL-25 or infection with the migratory helminth Nippostrongylus brasiliensis." (PMID 36052086, 2022). "In highly compatible hosts, such as mice, primary infection becomes chronic, while pharmacological healing of the primary infection induces a sudden production of IL-25." (PMID 36176223, 2022). "According to the new reports including theirs, the small intestinal tuft cells secrete the interleukin-25 (IL25) and leukotriene to the lamina propria to induce type-2 immunity on detecting the infection." (PMID 34994390, 2022). "In E. caproni infections in mice, interleukin-25 (IL-25) plays a critical role and it is required for the resistance to infection." (PMID 36176223, 2022). "To investigate the potential role of resident microbiota in the production of IL-25 and the subsequent resistance to infection we have used the experimental model of E. caproni in mice." (PMID 36176223, 2022). "Unlike intestinal tuft cells which are dependent on Th2 cytokines for their amplification, lung tuft cells arise in similar numbers in Il25-/- or Il4ra-/- mutants compared to controls following infection." (PMID 36073526, 2022). "Mice treated with exogenous IL-25 were protected from lethal infection, an effect that was dependent on the influx of CD11b+SiglecF+ eosinophils to the gut." (PMID 34360770, 2021). "ILC2s, a group of lineage negative non-antigen specific cells, produce IL-13 upon activation by the alarmin cytokines IL-25 and IL-33 during infection with helminths." (PMID 34578195, 2021). "In one study, anti-IL-33 treatment and TSLP receptor deficiency blocked the infection-induced expression of IL-25 in lung epithelial cells, and ex vivo treatment of ILC2 with TSLP increased their expression of IL-25 and IL-33 receptors." (PMID 33482904, 2021). "RV-C15 infection induced airway expression of IL-25, IL-33 and TSLP, innate cytokines responsible for activation of IL-5- and IL-13-producing ILC2s expansion." (PMID 33968043, 2021). "In a murine Clostridium difficile-infection (bacterial) model, cecal production of IL-25 resulted in the recruitment of eosinophils." (PMID 34578195, 2021).
infection (continued). "Susceptibility to primary infections was associated with low levels of intestinal IL-25 expression, whilst deworming by treatment with praziquantel induced a sudden increase in IL-25 expression preventing the establishment of secondary infections." (PMID 32616023, 2020). "Resistance to infection is due to the production of IL-25, which acts autonomously from Th2 response in terms of parasite clearance." (PMID 33276813, 2020). "Due to these elevated levels of IL-25 gene expression, mice became resistant to a challenge infection at 2 wppt, concomitantly with the development of a robust Th2 response." (PMID 33276813, 2020). "IL-25 response in secondary infections was higher, concomitantly with a more potent Th2 response and enhanced resistance to infection." (PMID 33276813, 2020). "Resistance to infection is due to IL-25, which acts autonomously from the Th2 response in the parasite clearance." (PMID 33276813, 2020). "Recent studies by our group have shown that partial resistance against E. caproni secondary infections in ICR mice is developed after the chemotherapeutic cure of a primary infection and that innately produced IL-25 is crucial to establishing resistance." (PMID 33276813, 2020). "Changes in cytokine expression in secondary infection at 2 wpsi in relation to the blockade of IL-25 were investigated by RT-PCR." (PMID 33276813, 2020). "In contrast, the lower levels of IL-25 overexpression to primary infections was reflected in a weak response of Th2 cytokines and chronic infections." (PMID 33276813, 2020). "In H. polygyrus infections, both primary and secondary infections included IL-25, but both responses were different." (PMID 33276813, 2020). "This supports that the processes related to oxidative stress and cell death are altered in the presence of infection by E. caproni independently of the presence and IL-25." (PMID 32616023, 2020). "Innate cytokines, including TSLP, IL-25 and IL-33, which are secreted following infection of murine and human airway epithelial cells by RSV, are known inducers of ILC2 differentiation and activation." (PMID 32375305, 2020). "The factors that determine the production of IL-25 in mice experimentally infected with E. caproni were determined, as were the consequences of IL-25 production in terms of polarization of the immune response and resistance to infection." (PMID 33276813, 2020). "To analyze the role of IL-25 in the generation of memory responses against resistance to E. caproni, we delayed the challenge infection until the levels of innate IL-25 gene expression upregulation declined to baseline, which occurred at 10 wppt." (PMID 33276813, 2020). "The observed increased IL-25 expression and determination of intestinal protein levels of IL-25 and IL-33 during infection with G. intestinalis warrants further investigation." (PMID 32283818, 2020). "A striking feature of E. caproni infections in mice is that tuft cell hyperplasia and the subsequent IL-25 overexpression exclusively occur as a consequence of the healing of the infection." (PMID 33276813, 2020). "Infection with this chronic gastrointestinal nematode has been shown to promote the release of host-derived IL-1β, which limits IL-25 production and the subsequent activation of ILC2s." (PMID 31024526, 2019). "iILC2s are recruited from the intestines in response to IL-25 or to an infection with N. brasiliensis." (PMID 31089134, 2019). "A population of IL-25 responsive KLRG1hi group 2 innate lymphoid cells, designated inflammatory ILC2s ‘iILC2’ was discovered in mice following infection." (PMID 29587679, 2018). "We then established that in C57BL/6 mice, IL-25 adminstered late in infection (days 14–17) drove immunity." (PMID 30238872, 2018). "Egg counts were equivalent at day 14 post-infection before delivery of IL-25 late and were significantly reduced in recipients of IL-25 early (66%; p=0.0013) or late (64%; p=0.0071) compared to PBS controls by day 28 post-infection." (PMID 30238872, 2018).
infection (continued). "LEPCs release innate cytokines, such as TSLP, IL-33, and IL-25, in response to infection or various environmental factors." (PMID 30056803, 2018). "Such a downstream role is consistent with recent reports demonstrating a role for IL-25 in protective immunity to a secondary infection with H. polygyrus, following drug clearance of a primary infection, or vaccination with parasite secreted antigens." (PMID 30238872, 2018). "The number of peritoneal monocytes was also significantly increased in response to IL-25, similar to the setting of H. polygyrus infection and a combination of infection and IL-25." (PMID 30238872, 2018). "To test whether IL-25-mediated promotion of immunity to primary H. polygyrus infection was entirely dependent upon IL-4Rα, or could mediate an IL-4Rα-independent mode of protection, we administered exogenous IL-25 from days 14–17 of infection to Il4ra-deficient mice." (PMID 30238872, 2018). "Our initial findings were also validated in vMC0-infected BN rats, where infection resulted in the induction of genes associated with macrophage M2 activation (MGL1, ARG1, IL10, and IL10RA) and Th2 genes (IL33 and IL25)." (PMID 30150981, 2018). "In IL-4-polarized macrophages, a further enhancement of infection was statistically significant for IL-25 alone, TSLP alone, and every combination of IL-33 with the other alarmins." (PMID 30282716, 2018). "In contrast, adult worm burden was significantly reduced in recipients of IL-25 late (66%; p=0.0016) at day 28 post-infection." (PMID 30238872, 2018). "In contrast, infection in an environment with elevated levels of IL-25, as occurs in challenge infection, results in a Th2 phenotype impairing parasite survival." (PMID 27658962, 2016). "In contrast, resistance to secondary infection appears to be related to the boost of IL-25 induced by the cure of the infection." (PMID 27658962, 2016). "Challenge infection in an environment with elevated levels of IL-25 resulted in a significantly lower infection rate and worm recovery than in primary infections." (PMID 27658962, 2016). "Together these studies show that immunization with secreted products from a gastrointestinal helminth induces long-lived sterile immunity against challenge infection through IgG1 antibodies acting in parallel with IL-4Rα- and IL-25-dependent effector cells." (PMID 25816012, 2015). "Similar methods revealed that IL-25 protected against infection with Trichinella spiralis, including reducing both the worm burden in the intestine and the number of larvae in the muscles." (PMID 25028340, 2014). "IL-25 mRNA is upregulated in the intestine following infection of N. brasiliensis, H. polygyrus bakeri, and T. muris." (PMID 24942690, 2014). "IL-4 cytokine levels peaked with the onset of microfilaremia at 60 dpi, whereas IL-5, IL-13 and IL-25 levels increased with the duration of infection." (PMID 24663956, 2014). "IL-25 deficient mice exhibited increased worm burdens at late time-points post-infection, indicating that even in the presence of normal IL-1β signaling low levels of IL-25 have a critical role in mediating worm expulsion." (PMID 23935505, 2013). "IL-1β acts to decrease production of IL-25 and IL-33 at early time points following infection and parasite rejection was determined to require IL-25." (PMID 23935505, 2013). "To assess the possible role of epithelial injury by early-life PVM infection in the induction of a Th2-biased immunological response, we assessed relative expression of mRNA for IL-25 in lung tissue at days 14 and 28 of life." (PMID 20122285, 2010). "Immunity could not be induced by IL‐33 administration in SCID mice lacking T and B cells, affirming that T cells rather than ILC2s are the likely drivers of immunity during HD Tm infection, as noted in IL‐25 administration." (PMID 40944312, 2025).
infection (continued). "A study in IL‐17RB knockout mice has shown increased faecal egg counts at days 14 and 18 post‐primary Hp infection, and impaired worm clearance following secondary Hp infection, suggesting a role for IL‐25 signalling to ILC2s in containing primary Hp infections and expelling secondary infections." (PMID 40944312, 2025). "IL-25 had been identified as an “alarmin” that could be induced by microbial colonization or infection, which implied that IL-25-mediated tuft cell training might occur periodically." (PMID 39261649, 2024). "Heterologous infection with RV2 on day 13 of life further increased IL-25 expression." (PMID 38061015, 2024). "Thus, our data suggested the potential collaboration of IL-25 and IL-33 in regulating adaptive T helper cell responses during C. neoformans infection, especially during the late phase of infection." (PMID 37337050, 2023). "Infection with some HPV types (i.e., high-risk HPV-35, -39, and -68) was associated with higher cervicovaginal cytokine concentrations, particularly of IL-17A, IL-17F, TNF-α, IL-25 and IFN-γ." (PMID 36992467, 2023). "However, partial resistance against secondary E. caproni infections in ICR (Institute of Cancer Research) mice is developed after the chemotherapeutic cure of a primary infection and the innately produced IL-25 after pharmacological treatment." (PMID 36176223, 2022). "Herein, we analyse the changes in resident microbiota induced by primary E. caproni infection in mice, cure of the primary and secondary infections with the aim to gain further insight into the potential role of microbiota in the production of IL-25 and resistance to infection." (PMID 36176223, 2022). "Mice undergoing RV-A1B infection alone showed increased mRNA and protein expression of IL-25 (seven days after secondary infection) and IL-33 (one day after secondary infection) compared to sham-infected mice, and heterologous infection with RV-A2 further increased innate cytokine expression." (PMID 36032072, 2022). "These cells are rare in naïve mice but are elicited by IL-25 stimulation and Nb infection." (PMID 35572538, 2022). "This indicates that resident microbiota may play a pivotal role in the expression of IL-25 and, consequently, in the resistance to challenge infections." (PMID 36176223, 2022). "For this purpose, we analysed the production of IL-25 under conditions of experimental dysbiosis and also the changes in the resident microbiota in primary infections, pharmacological curation and secondary infections." (PMID 36176223, 2022). "RV infection increased IL-25 gene expression at 2- and 4 days post-infection." (PMID 35508632, 2022). "Considering that several studies support that IL-25 production is mediated by signals derived from gut microbiota, we analyse the changes in the resident microbiota induced by a primary E. caproni infection and curation and a secondary infection." (PMID 36176223, 2022). "However, significant increases in IL-25 expression were detected in the pzq-treated and reinfected groups of mice as a consequence of treatment with pzq and healing of the primary infection (P < 0.05)." (PMID 36176223, 2022). "Compared to RV-A1B, RV-C15 infection induced significantly higher mRNA expression of IL-25." (PMID 33968043, 2021). "ETC-derived IL-25 may also act on immune cells such as macrophages and eosinophils and aid in the healing of the small intestine following infection with helminth parasites." (PMID 34578195, 2021). "It was reported that IL-22 could activate ILC3s indirectly by inducing epithelial IL-18 during infection and IL-25-expressing epithelial cells could suppress IL-22 production by ILC3s72,73." (PMID 34294718, 2021). "Specifically, nematode (Nippostrongylus brasiliensis) infection activates tuft cells and induces leukotriene C4 (LTC4) production, which activates ILC2s, in addition to IL-25 secretion, whereas protist (Trichuris muris) infection also activates tuft cells but only induces IL-25 production." (PMID 33403383, 2021).
infection (continued). "In addition, compared to RV-A1B, RV-C15 infection induced significantly higher protein expression of IL-25, IL-33 and TSLP." (PMID 33968043, 2021). "Our results indicate that IL-25 and E. caproni infection in the presence of rIL-25 induce proteomic changes in the ileum of mice that may contribute to resistance to infection." (PMID 32616023, 2020). "Herein, we analyze the proteomic changes induced by IL-25 that may contribute to resistance to infection." (PMID 32616023, 2020). "Despite the development of a type-2 response, mice are susceptible to secondary infection in relation to the lack of IL-25." (PMID 33276813, 2020). "However, blocking of the innately produced IL-25 after healing of the primary infection gave rise to a type-2 response as a consequence of the secondary infection, showing that IL-25 was not related to biasing of the immune response." (PMID 33276813, 2020). "However, both control animals and those with the blocked IL-13 receptors were refractory to primary infection due to the presence of exogenous IL-25." (PMID 33276813, 2020). "Susceptibility of mice relies in the inability of mice to produce IL-25 in response to infection." (PMID 33276813, 2020). "Looking back at this study, ILC2s can be directly implicated in this process as RAG-deficient mice (lacking B and T cells) given recombinant IL-25 cleared N. brasiliensis within 5 days of infection." (PMID 32793230, 2020). "Despite the development of a type-2 response, mice are susceptible to secondary infection associated with the lack of IL-25." (PMID 33276813, 2020). "The fact that expansion of GATA3+ cells exclusively occurs after a secondary infection in the presence of IL-25 may indicate that only the simultaneous combination of signals provided by the parasite and IL-25 are able to induce the polarization to Th2." (PMID 33276813, 2020). "Additionally, neonatal PVM-infected mice had increased lung levels of IL-25 at day 14 post-infection compared to un-infected mice." (PMID 32397226, 2020). "Although helminths are the focus here, other infections or insults that generate IL-25 and recruit iILC2s to the lung may similarly exacerbate allergic outcomes upon allergen exposure." (PMID 32793230, 2020). "Previous work has shown that IL-25 null mice are susceptible to a high single dose T. muris infection although no increase in IL-25 mRNA expression was found following infection in WT mice." (PMID 31730667, 2019). "Importantly, here we observe that pre-treatment of infected animals with anti-IL-23 completely reduces the rise in IL-25 levels observed during the infection in both PP and especially MSN." (PMID 29773890, 2018). "At day 14 post-infection, shortly after adult worms have matured, Il17rb-/- mice exhibited significantly increased egg production but equivalent adult worm burdens to the IL-25-sufficient wild-type BALB/c." (PMID 30238872, 2018). "Alarmins such as IL-25 are potent activators of type 2 immunity, but as we report here, can play an even more important role in stimulating and mobilising effector mechanisms to expel infection." (PMID 30238872, 2018). "Moreover, naive BN showed a Th2 bias following infection with vMC0, as shown by an influx of alternatively activated macrophages (MGL1/ARG1) with parallel upregulation of Th2-associated cytokines (IL25/IL33)." (PMID 30150981, 2018). "A requirement for IL-25/IL-25R signaling to expel H. polygyrus has previously been reported in other settings in which Th2 response levels appear unaffected, including both a vaccination model, and following drug-abbreviated primary infection." (PMID 30238872, 2018). "We confirmed that mucus secretion was disturbed with decreased IL-25 level at the site of infection in antibiotic pre-treated mice, which might allow more severe tissue invasion of E. histolytica." (PMID 28817707, 2017). "The results obtained indicate that susceptibility is determined by the lack of IL-25 expression in response to primary infection." (PMID 27658962, 2016).